PCGEM1 (PCGEM1 prostate-specific transcript)
Diseases named in the same sentence as PCGEM1 in open-access papers (continued):
Sharing a sentence is not in itself a finding about the gene and the disease.
glioma (2 papers, 2021 to 2022). A benign or malignant brain and spinal cord tumor that arises from glial cells (astrocytes, oligodendrocytes, ependymal cells). "In the past few years, PCGEM1 has been widely reported to be aberrantly expressed in various human cancers, such as glioma, oral carcinoma and EC." (PMID 35265529, 2022). "In glioma, the most common primary malignant cancer of the central nervous system, the expression of PCGEM1 was significantly elevated in higher WHO grade and the lower overall survival rate of patients." (PMID 35265529, 2022). "Further studies in other tumors reported that the tumor growth of the PCGEM1 groups was greater than that of the control groups in in vivo experiments of OC, EC and glioma." (PMID 35265529, 2022). "Our study for the first time defined the role of PCGEM1in glioma and illustrated the regulatory relationship between PCGEM1 and miR-539-5p/CDK6 axis." (PMID 33589577, 2021). "The expression of PCGEM1 in 43 glioma tissues and their corresponding adjacent normal tissues was analyzed through qRT-PCR." (PMID 33589577, 2021). "Summarily, our findings suggest that PCGEM1 plays oncogenic functions in glioma cells through modulating miR-539-5p/CDK6 pathway." (PMID 33589577, 2021). "MiR-539-5p mimics repressed glioma progression while CDK6 overexpression reversed the roles of PCGEM1 knockdown." (PMID 33589577, 2021). "This study aims to research the functional mechanism of lncRNA PCGEM1 involved in glioma progression." (PMID 33589577, 2021). "We found that miR-539-5p is sponged by PCGEM1 and its upregulation suppressed glioma cell growth, migration and invasion." (PMID 33589577, 2021). "Results showed that PCGEM1 level was increased in glioma tissues, which was confirmed by Northern blot analysis." (PMID 33589577, 2021). "And PCGEM1 knockdown repressed the proliferation, migration and invasion of glioma cells, suggesting PCGEM1 is an oncogene." (PMID 33589577, 2021). "We demonstrated that PCGEM1 level was increased in glioma tissues and its knockdown suppressed glioma proliferation, migration and invasion in vitro." (PMID 33589577, 2021). "qRT-PCR results also indicated that miR-539-5p expression was reversely correlated with PCGEM1 in glioma tissues." (PMID 33589577, 2021). "Colony formation assay also confirmed that PCGEM1 knockdown inhibited glioma cell proliferation." (PMID 33589577, 2021). "In sum, the present research discovered that PCGEM1 was an oncogene in glioma by modulating miR-539-5p/CDK6 pathway, suggesting that PCGEM1 may be a novel therapeutic target." (PMID 33589577, 2021). "Finally, the survival rate of patients with glioma observed in the clinic was analyzed based on PCGEM1 expression." (PMID 33589577, 2021). "In this study, it was found that PCGEM1 was upregulated in glioma tissues and cell lines." (PMID 33589577, 2021). "PCGEM1 knockdown suppressed the proliferation, migration and invasion of glioma cells." (PMID 33589577, 2021). "Moreover, we revealed that CDK6 was regulated by PCGEM1 through inhibiting miR-539-5p in glioma cells." (PMID 33589577, 2021). "This study identified that PCGEM1 was upregulated in glioma tissues and cells." (PMID 33589577, 2021). "qRT-PCR found that PCGEM1 levels were raised in glioma cell lines compared to NHA cells." (PMID 33589577, 2021). "qRT-PCR indicated that PCGEM1 expression was higher in glioma tissues with graded III/IV." (PMID 33589577, 2021). "Results from CCK8 assay showed that PCGEM1 knockdown delayed glioma cell growth." (PMID 33589577, 2021). "And PCGEM1 upregulation predicted poor prognosis in glioma patients." (PMID 33589577, 2021). "Our study for the first time explored the role of PCGEM1 in glioma cells." (PMID 33589577, 2021). "Therefore, PCGEM1 regulates miR-539-5p/CDK6 axis to promote glioma progression." (PMID 33589577, 2021).
glioma (continued). "Other researchers demonstrated that PCGEM1 facilitates cell proliferation and colony formation through the miR-148a/TGFβ2/Smad2, miR-539-5p/CDK6 and miR-129-5p/STAT3 axes in OC, glioma and EC, respectively." (PMID 35265529, 2022). "Results showed that either PCGEM1 knockdown or miR-539-5p mimics suppressed glioma cell proliferation, migration and invasion while CDK6 overexpression reversed the effects of PCGEM1 knockdown." (PMID 33589577, 2021).
hepatocellular carcinoma (2 papers, 2016 to 2022). A malignant tumor that arises from hepatocytes. "PCGEM1 was also reported to modulate oxaliplatin resistance in hepatocellular carcinoma (HCC)." (PMID 35265529, 2022).
lymph node metastasis (2 papers, 2022). "Moreover, PCGEM1 expression is closely associated with TNM stage (P=0.020) and lymph node metastasis (P=0.034)." (PMID 35265529, 2022).
schizophrenia (2 papers, 2013 to 2014). A major psychotic disorder characterized by abnormalities in the perception or expression of reality. "Three of the 17 schizophrenia genome-wide significant SNPs tested showed some evidence of association with definite psychotic experiences (MIR137 rs1625579 on chromosome 1, P = .012; intergenic SNP rs17662626 near PCGEM1 on chromosome 2, P = .017; and NT5C2 rs11191580 on chromosome 10, P = .036)." (PMID 24174267, 2014).
acute myeloid leukemia (1 paper, 2022). Acute myeloid leukemia (AML) is a group of neoplasms arising from precursor cells committed to the myeloid cell-line differentiation. "For example, lncRNAs PCA3, PCGEM1, and PCAT-1 are highly expressed in prostate cancer, and the expression level of KIAA0125 correlated negatively with the prognosis of acute myeloid leukemia (AML)." (PMID 36591508, 2022).
airway hyperresponsiveness (1 paper, 2020). "The in vivo experimentsdemonstrated that upregulation of PCGEM1 strengthened the protective effects ofmontelukast sodium on pulmonary function by reducing airway hyperresponsiveness andincreasing FEV0.4/FVC." (PMID 32520202, 2020).
asthma (1 paper, 2020). "Further, the ROC curveanalysis showed that PCGEM1 had a diagnostic value for asthma." (PMID 32520202, 2020). "lncRNAs are reported to be involved in the regulation of inflammatory mediatorsor the expression of cytokines.lncRNA PCGEM1 is lowly expressed in the serum of asthma patients." (PMID 32520202, 2020). "A preliminaryscreening of dysregulated lncRNAs presents a low expression of PCGEM1 in the serumsamples of patients with asthma." (PMID 32520202, 2020). "Asthmatic mice experienced nasal inhalation ofPCGEM1 overexpression with simultaneous montelukast sodium to investigate theroles of PCGEM1 in asthma treatment." (PMID 32520202, 2020). "Therefore,this study aimed to investigate the effect of montelukast sodium on childrenwith cough-variant asthma (CVA) and the role of lncRNA prostate cancer geneexpression marker 1 (PCGEM1) in drug efficacy." (PMID 32520202, 2020). "Finally, upregulation of PCGEM1 combined with montelukast sodium treatment blockedthe activation of NF-κB mRNA and protein after asthma induction." (PMID 32520202, 2020). "Also,we suggest that lncRNA PCGEM1 potentiated the therapeutic effect of montelukastsodium on asthma by blocking the NF-κB signaling pathway." (PMID 32520202, 2020).
endometriosis (1 paper, 2023). The growth of functional endometrial tissue in anatomic sites outside the uterine body. "In this study, we established an endometriosis rat model, isolated ESCs and primary NESCs and studied the potential role of PCGEM1 in endometriosis." (PMID 36915057, 2023). "In the present study, bioinformatics analysis and molecular and animal experiments were employed to explore the functions of PCGEM1 in the pathogenesis of endometriosis." (PMID 36915057, 2023). "To determine the potential role of lncRNA PCGEM1 in endometriosis, we established an endometriosis model in SD rats." (PMID 36915057, 2023). "Bioinformatics analysis was adopted to study the roles of PCGEM1 in promoting the pathogenesis of endometriosis." (PMID 36915057, 2023). "The PCGEM1/miR-124-3p/ANTXR2 regulatory network is likely to be a novel therapeutic target in endometriosis." (PMID 36915057, 2023). "We investigated the potential roles of PCGEM1 in the pathogenesis of endometriosis." (PMID 36915057, 2023). "PCGEM1 can influence endometrial stromal cell proliferation and motility and may be a novel therapeutic target for endometriosis." (PMID 36915057, 2023). "PCGEM1 promotes cell proliferation and migration in endometriosis." (PMID 36915057, 2023). "Our study indicated that PCGEM1 may be a novel therapeutic target for endometriosis." (PMID 36915057, 2023). "Taken together, these findings indicate that the lncRNA PCGEM1 and ANTXR2 are overexpressed in endometriosis." (PMID 36915057, 2023). "To interpret the biological functionality of the lncRNA PCGEM1 and anthrax toxin receptor 2 (ANTXR2) in endometriosis, we measured the PCGEM1 and ANTXR2 relative mRNA and protein expression levels in 10 paired ectopic (NE) and eutopic (Eu) endometrial tissues by qRT‒PCR and Western blot analysis." (PMID 36915057, 2023).
rheumatic diseases (1 paper, 2023). "Some research, such as exosomal PCGEM1, may fill the gap in the early diagnosis of rheumatic diseases." (PMID 38107573, 2023).
cancer (43 papers, 2014 to 2024). A tumor composed of atypical neoplastic, often pleomorphic cells that invade other tissues. "In this review, we will retrospectively review the recent studies of the expression of lncRNA PCGEM1 in human cancers and comprehensively describe the underlying regulatory mechanism by which PCGEM1 functions in tumors." (PMID 35265529, 2022). "In terms of the underlying mechanisms, diverse modes of PCGEM1 action in various cancers with different regulatory factors and downstream signaling pathways or molecules have been investigated in various cancer types." (PMID 35265529, 2022). "PCGEM1 prostate-specific transcript (PCGEM1) is the lncRNA which is associated with the progression of several cancers." (PMID 32787827, 2020). "Prostate cancer–associated 3 (PCA3) and prostate cancer gene expression marker 1 (PCGEM1) were the first discovered cancer-associated lncRNAs." (PMID 33281872, 2020). "Polymorphisms on the highly cancer-associated lncRNA PCGEM1 was also suggested to contribute to cancer risk in Chinese men." (PMID 26690121, 2015). "The association of PCGEM1 with prostate oncogenesis, in particular, is supported by its overexpression in prostate tumors that was repeatedly observed, and by its function in enhancing cancer cell survival, proliferation, invasion, and metabolic regulation." (PMID 26690121, 2015). "Prostate cancer gene expression marker 1 (PCGEM1) can activate androgen receptors indicating its tumorigenic potential." (PMID 37161350, 2023). "The tumor-promoting lncRNA PCGEM1 regulates cancer cell metabolism by promoting the chromatin recruitment of c-Myc and increasing its transactivation activity." (PMID 36293081, 2022). "(V) Looping enhancers and regulating genome organization; for instance, prostate cancer-associated noncoding RNA 1 (PRNCR1) and prostate-specific transcript (PCGEM1) are two lncRNAs that increase the enhancer-promoter looping in cancer cells." (PMID 35359941, 2022). "Hypoxic cancer cells are sources of plentiful amounts of exosomal PCGEM1, which can be internalized into normoxic cancel cells." (PMID 35055115, 2022). "Prostate cancer gene expression marker 1 (PCGEM1) has abnormal expression level in a variety of malignant tumor." (PMID 36193492, 2022). "Studies found that prostate cancer gene expression marker 1 (PCGEM1) with highly prostate-specificity was also related to androgen receptor (AR) signaling and was overexpressed in therapy-resistant PCa." (PMID 36514044, 2022). "In this section, we will discuss the aberrant expression of PCGEM1 in clinical samples from cancer patients with an emphasis on the correlated clinical features and cancer growth traits in tumor xenograft models." (PMID 35265529, 2022). "Herein, we summarized the recent progress regarding the dysregulation and cancer-related functions of PCGEM1 in cell lines and clinical samples of different types of cancer." (PMID 35265529, 2022). "Generally, PCGEM1 facilitates oncogenic pathophysiologic processes such as cancer cell proliferation and invasion through multiple axes or key modulators." (PMID 35265529, 2022). "Prostate cancer gene expression marker 1 (PCGEM1) is a lncRNA specifically expressed within the prostate and overexpressed in many cancer cells." (PMID 35109849, 2022). "Metastasis is the dominant cause of advanced tumor stage, and enhanced cell invasion and migration and PCGEM1 overexpression have been observed in diverse cancer cell lines." (PMID 35265529, 2022). "More importantly, based on the relationship between PCGEM1 and cancers, the potential application of PCGEM1 in clinical diagnosis, prognosis and therapeutic treatment will also be highlighted." (PMID 35265529, 2022). "Hypoxic cancer cells contain large amounts of exosomal lncRNA PCGEM1, which plays a crucial role in proliferation, migration, invasion, drug resistance, and angiogenesis in cancer." (PMID 36038612, 2022).
cancer (continued). "Even in a given cancer type, such as PC, PCGEM1 functions in various ways, including the lncRNA-miRNA-mRNA network and interaction with transcription factors." (PMID 35265529, 2022). "Through diverse functional mechanisms, PCGEM1 has a large effect on downstream genes and then regulates cancer cell proliferation, invasion and apoptosis." (PMID 35265529, 2022). "PCGEM1 prostate-specific transcript (PCGEM1) is an lncRNA which has been searched in several cancer types." (PMID 32787827, 2020). "Recently, lncRNA prostate cancer gene expression marker 1 (PCGEM1) has been identified as an oncogenic gene in human cancers." (PMID 31832017, 2019). "For example, lncRNA PCGEM1, by directly interacting with c-Myc and being a coactivator for c-Myc, functions as a master regulator of metabolic reprogramming in cancer." (PMID 31488218, 2019). "Recently, long noncoding RNA (lncRNA) prostate cancer gene expression marker 1 (PCGEM1) has been demonstrated to involve in the initiation and progression of human cancers." (PMID 31832017, 2019). "PCGEM1 participates in multiple pathways that impact on cancer growth including repression of the tumour suppressor miR-145." (PMID 28035996, 2016). "For example, metastasis-associated lung adenocarcinoma transcript 1 (MALAT1), prostate cancer associated non-coding RNA 1 (PRNCR1), prostate cancer gene expression marker 1 (PCGEM1), H19, and several new lncRNAs involve in glioma development." (PMID 26172293, 2015). "PCGEM1 is overexpressed in prostate cancer and is pivotal in cancer metabolism regulation." (PMID 37161350, 2023). "Functions and upstream/downstream regulators of PCGEM1 in various cancer cell lines." (PMID 35265529, 2022). "lncRNA PCGEM1 has been proved to participate in the progress of several cancers." (PMID 36193492, 2022). "Expression files of PCGEM1 and relevant clinicopathological features in various cancers." (PMID 35265529, 2022). "Functional analysis also revealed that multiple biological effects, including proliferation, invasion and migration, apoptosis, drug resistance and metabolism of cancer cells, could be potently modulated by PCGEM1 overexpression." (PMID 35265529, 2022). "In addition, the correlation between PCGEM1 and survival prognosis and cancer metastasis in PCa patients requires further study." (PMID 35412947, 2022). "This is demonstrated by the sequential assembly of Prostate cancer associated non-coding RNA 1 (PRNCR1) and lncRNA prostate cancer gene expression marker 1 (PCGEM1) with the androgen receptor (AR), the MEG3 structure required for its tumor suppressive function." (PMID 34504983, 2021). "In addition to PCGEM1, lincRNA-p21 was also revealed to be an important regulator of the Warburg effect in cancer cells, essential for hypoxia-enhanced glycolysis and tumor cell growth." (PMID 26690121, 2015). "In NSCLC, PCGEM1 could boost cancer cells proliferation by improving WTAP expression." (PMID 36324565, 2022). "Herein, the specific relationship between PCGEM1/miR-129-5p/CDT1 in PCa was verified, and its effect on cancer cell biological function was discussed." (PMID 35412947, 2022). "Exosomal PCGEM1 leads to an increase in SNAI1 levels and expedites migration and invasion in normoxic cancer cells." (PMID 35055115, 2022). "And many studies have shown that the high expression of PCGEM1 and PHYHD1 can promote the value-added migration and invasion of cancer, affecting prognosis." (PMID 36313300, 2022). "Pearson correlation analysis also confirmed a negative correlation between PCGEM1 and miR-129-5p in cancer." (PMID 35412947, 2022). "Finally, while PCGEM1 is upregulated in cancer patients from matched tumor/benign samples, PRNCR1 does not convincingly exhibit this pattern of upregulation." (PMID 24727738, 2014).